NRP1 (neuropilin 1)
Diseases named in the same sentence as NRP1 in open-access papers (continued):
Sharing a sentence is not in itself a finding about the gene and the disease.
tumor (continued). "NRP1 expression was confirmed on the U87MG tumor tissue used in the present study." (PMID 26398657, 2015). "MiR-148a was found to bring about tumor-suppressive effect by targeting NRP1, ROCK1 and DNMT1." (PMID 26097868, 2015). "However, the occurrence of NRP-1 protein positive granules was lower in cells of the poor tumor cell differentiation group than both moderate and well tumor cell differentiation groups (P < 0.05, resp)." (PMID 25873749, 2015). "Although the loss of NRP1's cytoplasmic tail had a small effect on tumour angiogenesis in β3-WT mice, this did not translate to an overall difference in tumour growth." (PMID 26159543, 2015). "In general, NRP1 may mediate the effects of miR-338 on tumor progression indirectly by affecting angiogenesis, or directly, through its effects on tumor cells." (PMID 24736504, 2014). "Moreover, research has shown that NRP-1 inhibitors provide an additive effect to anti-VEGF therapy in reducing tumor progression." (PMID 24669769, 2014). "Indeed, it remains a remarkable observation that blocking the function of one molecule (e.g., Nrp-1) in one cell type (the macrophage) is able to dramatically impact the behavior of a very complex tissue such as a tumor." (PMID 24723924, 2014). "Conversely, a role for Nrp1 expression on CD8+ T cells that is distinct from tolerance might emerge under conditions in which tumor is present." (PMID 25343644, 2014). "In addition, NF-κB activation is also responsible for tumor mammosphere formation, which was shown to be dependent on NRP1 expression." (PMID 24999732, 2014). "Furthermore, among the tumor specimens, there was a significant correlation between higher NRP-1 expression levels and lymph node metastasis (P = 0.007)." (PMID 24999732, 2014). "Peritumoral NRP-1 and VEGFR-2 expression were significantly higher than that of the tumoral tissue (p < 0.001 for both), and high peritumoral expression of both factors was negatively associated with tumor size (p < 0.001 for both)." (PMID 25333267, 2014). "Previous studies showed that NRP1 overexpression in several malignances may contribute to local tumor invasiveness and migration." (PMID 24999732, 2014). "The forced expression of miR-338 significantly inhibited tumor growth in vivo, but the overexpression of NRP1 could restore tumor growth." (PMID 24736504, 2014). "This has important clinical repercussions, as Nrp1 is being targeted therapeutically in cancer patients but the mechanism by which this strategy might enhance anti-tumor immunity is not completely understood." (PMID 25343644, 2014). "NRP1 plays a critical part in neuronal development, in angiogenesis and tumor invasion." (PMID 24058270, 2013). "In conclusion, our data show for the first time that NRP-1 upregulation may be a novel biomarker for the prediction of advanced tumor progression and unfavorable prognosis in NPC patients who may benefit from alternative treatment strategy." (PMID 24053763, 2013). "Therefore, a novel iRGD peptide has been recently identified and reported to increase vascular and tissue penetration in a tumor-specific and neuropilin-1- (NRP-1-) dependent manner." (PMID 23691500, 2013). "Interestingly, the frequencies of CD4+Nrp1+CD25high T cells were reduced in the tumor-draining lymph nodes of cervical cancer patients after chemoradiation therapy, which was associated with a decrease in the tumor mass." (PMID 24324469, 2013). "Protein expression of NRP-1 in tumor tissues was detected by western blot assay." (PMID 23251257, 2013). "Thus, a promising development surfaced, whereby it was reported that antibodies to NRP-1 in combination with anti-VEGF enhanced the ability of anti-VEGF to block tumor growth." (PMID 24385810, 2013). "In vivo, NRP-1 knockdown in tumor tissues resulted in decreased vasculature." (PMID 23251257, 2013). "Recent studies have indicated that the overexpression of NRP-1 may enhance tumor angiogenesis and tumor growth in vivo." (PMID 24053763, 2013).
tumor (continued). "Importantly, Nrp-1 is frequently expressed by tumour cells and is involved in their malignant progression." (PMID 23585849, 2013). "High NRP-1 expression was observed in tumor cells of 66.17% (176/266) NPCs." (PMID 24053763, 2013). "The enhanced expression of VEGF165 by the hypoxia-primed HT1080 cells, the HIF-1α-dependent tubule formation seen in the earlier experiments and the formation of vessel-like structures by the tumour cells in vivo prompted us to look for the expression of NRP-1 in the hypoxia-primed cells." (PMID 23185562, 2012). "This suppressive role of Nrp1 is particularly relevant to cancer, where it could block anti-tumor immunity." (PMID 22948112, 2012). "NRP1: Among the 15 normal tongue epithelium tissues, only 3 (20%) showed positive NRP1 expression, while positive staining was observed in 38/43 (88.3%) tumour specimens." (PMID 22926477, 2012). "Interaction between VEGF and one of its co-receptor neuropilin 1 (NRP1) is known to play an important role in tumor angiogenesis and therefore blocking their interaction could be a rational anti-angiogenic therapeutic approach for cancer treatment." (PMID 22448259, 2012). "NRP-1 is a co-receptor of VEGFR-2 and it specifically increases the binding of its ligand VEGF165, the predominant splice variant of VEGF-A playing an important role in tumour growth and angiogenesis." (PMID 23185562, 2012). "NRP-1 may either mediate its effects on the tumour progression indirectly by promoting tumour angiogenesis or directly by affecting the biology of the tumour cells themselves." (PMID 23185562, 2012). "Blocking NRP1 in mice exposed to cancer cells, resulted in a vascular-specific anti-tumor activity." (PMID 21747928, 2011). "Moreover, NRP1-Sema3B interactions induce high level of IL-8 in tumor cells, leading to a massive monocyte/macrophage recruitment, promoting invasion and metastasis formation." (PMID 24212788, 2011). "Indeed, Fukasawa and colleagues show that NRP1 interacts with integrin-β1 in pancreatic ductal adenocarcinoma and in this way promotes tumor cell growth, survival and invasion." (PMID 24212788, 2011). "Indeed, Sugahara and collaborators reported two tissue-penetrating peptides binding human integrins and NRP1 capable of penetrating into tumor tissue and cells." (PMID 24212788, 2011). "Furthermore, NRP2 siRNA also decreased tumour cell migration, and combined transfection with NRP1 and NRP2 siRNAs had a greater effect." (PMID 20087344, 2010). "It is therefore unclear whether NRP1 is important for tumour cell functions relevant for neoplastic growth and metastatic spread." (PMID 20087344, 2010). "Neuropilin-1 (NRP1) is a non-tyrosine kinase receptor for vascular endothelial growth factor (VEGF) recently implicated in tumour functions." (PMID 20087344, 2010). "In support of this study, targeting tumor cell-secreted PDGF-B or NRP-1 in pericytes by inhibitors may efficiently diminish the tumor angiogenesis, tumor growth and metastatic spread." (PMID 20687910, 2010). "Our results indicate that an important mechanism through which NRP1 antagonism may inhibit tumour cell migration is by reducing cell adhesion to ECM." (PMID 20087344, 2010). "The present study suggests that peptide antagonists of NRP1 may be therapeutically useful for preventing tumour cell functions required for metastasis and tumour spread." (PMID 20087344, 2010). "Since NRP1 has been strongly implicated in the migratory response to VEGF in endothelial cells, initially we examined the effects of EG3287 on tumour cell chemotaxis induced by VEGF." (PMID 20087344, 2010). "It is possible, therefore, that NRP1 antagonists and siRNAs could indirectly affect tumour cell function by impairing functional signalling mediated via other receptors such as c-Met." (PMID 20087344, 2010). "However, the propensity to bind to NRP1 is much higher in tumor for a density of 100,000 NRP1 per endothelial cell." (PMID 18713470, 2008).
tumor (continued). "In particular, the higher the NRP1 density in tumor, the less the binding to VEGFR1 and VEGFR2." (PMID 18713470, 2008). "Besides VEGF binding, a novel mechanism was recently proposed for NRP1 to promote tumour progression through the enhancement of autocrine hepatocyte growth factor/scatter factor signalling through c-Met." (PMID 18781179, 2008). "Finally, the model showed that the higher the NRP1 density in tumor, the less the binding to VEGFR1 and VEGFR2." (PMID 18713470, 2008). "Indeed, more recent studies suggest that NRP-1 functions in tumour cells other than as a VEGFR co-receptor." (PMID 15956974, 2005). "Thus, the mechanisms by which NRP-1 induces functional changes in tumour cells require further elucidation." (PMID 15956974, 2005). "Among the differentiated tumours, half of them expressed nrp-1 and two-thirds expressed egf-r." (PMID 12618892, 2003). "Two of the six intestinal-type tumours demonstrated colocalisation of NRP-1 and EGF-R." (PMID 12618892, 2003). "Furthermore, NRP-1 has been found to be expressed by tumour cells and has been shown to enhance tumour angiogenesis and growth in preclinical models." (PMID 12618892, 2003). "Alternatively, VEGF-165 might stimulate tumour cells directly via NRP-1 through an unknown mechanism." (PMID 12618892, 2003). "We investigated whether the tumor-penetrating peptide iRGD enhances anti-programmed cell death protein 1 (PD-1) treatment efficacy and examined the clinical relevance of neuropilin 1 (NRP1) expression." (PMID 42166776, 2026). "Moreover, NRP1 is upregulated in variety of tumor types, including TNBC and CRC." (PMID 40048021, 2025). "Therefore, the newly designed CPP (RKKRRQRRRdGR) could bind to integrin αvβ3 and NRP-1 with improved tumor targeting and tissue penetrating capabilities." (PMID 40019229, 2025). "The enhanced penetration was suppressed by a co-treatment with a Neuropilin-1 inhibitor, and the fluorescence signals from intratumorally injected SAPSp-iRGD-lipo were localized in Neuropilin-1-expressing regions, indicating a Neuropilin-1-mediated tumor penetration." (PMID 41295604, 2025). "Therefore, inhibiting NRP1 in ECSs can decrease the development and motility of tumor cells." (PMID 40277760, 2025). "Therefore, molecular targeting of NRP1 could prove to be effective as it plays an essential role in tumor invasiveness and mobility of CSCs." (PMID 40277760, 2025). "Contrasting new evidence has shown that NRP1 can also be considered an angiogenesis mediator in tumors, suggesting that tumor growth and metastasis may be the product of molecular interactions between NRP1’s originally deduced process of neuronal guidance and angiogenesis." (PMID 40277760, 2025). "However, NRP1− macrophages appear to maintain a more pro-inflammatory, anti-tumour phenotype." (PMID 40134439, 2025). "Hence, the NRP-1 peptide antagonist may offer greater potential for tumor penetration than the current treatment involving anti-NRP-1 antibodies." (PMID 40430075, 2025). "Noteworthily, the high-risk group indicated lower expression levels of CD200, NRP1, and TNFRSF14, suggesting that tumor cells might evade immune surveillance through inhibiting the function of these immune checkpoint genes, which could subsequently affect patient prognosis." (PMID 40365116, 2025). "Besides, NRP1 protein level also was higher in BCa tumor tissues and cell lines." (PMID 39014364, 2024). "We hypothesized that the reason T cell immunity was enhanced by NRP1-deficiency in our tumor models, but not against H7N1 S-flu, was an increased availability of SEMA3A in the former." (PMID 38609390, 2024). "NRP1 is associated with increased matrix stiffness by promoting fibronectin reorganization and collagen secretion, mediated by its role as a coreceptor for β1 integrins and TGF-β1; the last one a relevant growth factor for myofibroblasts recruitment and tumor fibrotic response." (PMID 38903533, 2024).
tumor (continued). "Furthermore, Sema3A selective mutants, which can competitively interact with PlexinA4 and prevent neuropilin-1/PlexinA4 interactions have also been shown to accelerate vascular normalization and reduce tissue hypoxia, increase perfusion and inhibit tumor growth in a mouse model of pancreatic cancer." (PMID 38375479, 2024). "We hypothesized that NRP1 may contribute to the formation of radiation resistance in tumor cells." (PMID 39187525, 2024). "Hence, NRP-1 mediated targeted therapy may be a potential strategy for precise TNBC therapy by simultaneously targeting tumor cells and vascular endothelial cells." (PMID 36902076, 2023). "Moreover, decreases in NRP1 levels were directly correlated with tumor mass reduction." (PMID 37371647, 2023). "Finally, in order to investigate whether NRP1 affects tumour growth in vivo, a nude mouse xenograft tumour model was constructed for this purpose." (PMID 37702613, 2023). "During this process, hypoxia and LA regulate the effects of TAMs on the tumor-associated blood vessels via finely tuning the activation of TAMs and stimulating pro-angiogenic gene transcription in a HIF-α–dependent manner, such as VEGFA, TIE2, and neuropilin-1 (NRP1)." (PMID 38274812, 2023). "Thus, using RGERPPR as an example, they showed that both topoisomers were superior, with the e version (rGerppr) displaying higher stability and stronger binding to NRP-1 than the L-peptide and the re version (rppreGr) demonstrating heightened tumor-penetrating prowess and stability." (PMID 37896211, 2023). "The enhanced in vivo (1.6 times higher 1 h after injection) and ex vivo (1.9 times higher) tumour uptake of the iNGR derivative is consistent with previous research, where the two-fold higher cellular uptake ratio of the dual-modified liposomes was due to attachment to NRP-1." (PMID 37628856, 2023). "Additionally, we observed that mATC cells overexpressed receptors such as FGFR1, EPHB2, PDGFRA, NOTCH3, ANTXR1, and NRP1, which could receive signals from CAFs and thereby promote tumor cell proliferation and aggressiveness." (PMID 37053016, 2023). "In addition, NRP1 expression is induced in PBMCs co-cultured in vitro with tumor tissue." (PMID 37894289, 2023). "Interestingly, Nrp1 was also significantly decreased on Tconv cells in the tumor, showing that reduced TGFβ signaling may affect other cell types as well, although overall Nrp1 levels were overall much lower than what is observed on Treg cells." (PMID 37552475, 2023). "Therefore, neuropilin-1 might have a dual, contextual, and tumor-type-specific immunomodulatory role in cancer and immunotherapy." (PMID 36672243, 2023). "To determine whether NRP1 targeting can elicit strong antitumor effects in a broad range of GBMs, we performed in vivo growth competition assays in which control (GFP-labeled) or NRP1 shRNA (RFP-labeled) tumor cells were mixed in a 1:1 ratio and coinjected into mouse brains." (PMID 37788099, 2023). "Similarly, in vivo experiments have shown that NRP1 can affect tumour growth in vivo." (PMID 37702613, 2023). "Higher iNGR uptake of the HT1080 cells—experienced at every investigated time point of the cell binding assay where the mechanism of NRP-1 could be expressed—indicates the better tumour-homing ability of the internalising peptide compared to the NGR counterpart." (PMID 37628856, 2023). "It has been described that NRP1 could drive not only tumor progression but also tumor pathogenesis." (PMID 35884516, 2022). "By adding a magnetic field to the tumor area, the obtained magnetic targeting procoagulant protein (MTPCP) could be quickly enriched in the tumor vessels and further bound to NRP-1 of TVEC by EG3287, resulting in the selective generation of coagulation in tumor-associated blood vessels." (PMID 35858896, 2022).
tumor (continued). "These neovascular implications may worsen tumor progression through alterations in the Nrp1/VEGFR2 complex arrangements, expression of pro-inflammatory cytokines, and a reduction in endothelial maturation factors which would otherwise result in a static phenotype." (PMID 36203599, 2022). "Thus, inhibition of Nrp1 may have protective effects in areas of hypoxia, which may be of utmost importance in an area of tumor cells as hypoxia regions are frequently present." (PMID 36203599, 2022). "Neuropilin-1 is a non-tyrosine kinase receptor implicated in tumor progression." (PMID 35303925, 2022). "Therefore, concomitant blockade of semaphorins, Nrp-1, and PD-1 may reshape the anti-tumor function of CTL and abrogate tumor progression." (PMID 35155237, 2022). "On the one hand, RGD (arginine-glycine-aspartic acid) may interact with the overexpressed v3 integrin in tumor vasculature to target tumor endothelium; on the other, RGDK can bind to the neuropilin-1 (Nrp-1) receptor on tumor cells, facilitating cancer cell penetration and uptake." (PMID 36091772, 2022). "Thus, Nrp1 appears to promote chemoresistance in a variety of tumor models, yet the mechanisms behind resistance appear to be variable depending on the nature of the tumor." (PMID 36203599, 2022). "We can speculate that the non-response with the 2 weeks treatment is possibly due to a selection of resistant tumor cells to NRP1 inhibition or to other mechanisms of escape involving vascularization which are well-known to targeted therapies promoting other signaling pathways." (PMID 36457009, 2022). "Targeting IDO and/or NRP1 may promote tumor infiltration and generate a less suppressive TME." (PMID 34177968, 2021). "IFNγ produced by converted Treg cells and CD8 T cells after αPD1 + αGITR combination therapy may also have an additional effect of driving the reprogramming of subsequent waves of tumor Treg cells, as suggested by observations made in the context of Helios−/−, NRP1−/−, and/or CARMA−/− Treg cells." (PMID 33976133, 2021). "Considering the importance of NRP1 in tumor development and its relevance to RCC1 in a variety of tumors, combined with RCC1 involved in CAF and the tumor infiltration of CD8+ T cells, we believe that RCC1 might be a potential new tumor target involved in the immunosuppressive function of NRP1." (PMID 34298996, 2021). "Additionally in the VEGF family ligand-receptor interactions pathway, VEGFR1 (log2 fold change = −2.38) was upregulated in the HCC tumor while NRP1 (log2 fold change = 4.93), VEGFR2 (log2 fold change = 2.76), and VEGFR3 (log2 fold change = 3.21) were upregulated in the TME." (PMID 33995488, 2021). "Thus, NRP1 intra- and extracellular domains, through the activation of c-Abl and α5β1 integrin, increase fibronectin fibril assembly contributing to matrix stiffness and tumor progression and invasiveness." (PMID 32766254, 2020). "Additionally, PLT-combined administration with ginsenoside compound K (CK), using the tumor-targeting carriers tLyp1 liposomes, was found to enhance tissue penetration and selectively target neuropilin-1 on the surface of lung cancer cells, thus facilitating the delivery of PTL and CK to the tumor." (PMID 33202681, 2020). "Cryptic CendR peptides home to tumor vasculature by binding to the receptor expressed selectively on tumor endothelium, where they are cleaved by proteases and the cryptic CendR motif is exposed, after which it can bind to NRP-1 for efficient cell and tissue penetration." (PMID 32497513, 2020). "Thus, the assessment of NRP1 expression in tumor biopsies could be used as a surrogate indicator of its targetability in selected patients." (PMID 32784465, 2020). "In addition, NRP1 is up-regulated in clinical tumor samples." (PMID 33239293, 2020).